FABP4 (fatty acid binding protein 4)
Diseases named in the same sentence as FABP4 in open-access papers (continued):
Sharing a sentence is not in itself a finding about the gene and the disease.
acute myocardial infarction (5 papers, 2019 to 2024). Necrosis of the myocardium, as a result of interruption of the blood supply to the area. "Interestingly, one study reported significantly elevated FABP4 levels during the early hours after the occurrence of acute myocardial infarction." (PMID 30969942, 2019). "In addition, increased serum levels of FGF21 have been observed in patients with acute myocardial infarction (AMI), along with higher serum fatty acid binding protein-4 (FABP4) and saturated fatty acid levels." (PMID 37667400, 2023).
atrial fibrillation (5 papers, 2011 to 2024). A disorder characterized by an electrocardiographic finding of a supraventricular arrhythmia characterized by the replacement of consistent P waves by rapid oscillations or fibrillatory waves that vary in size, shape and timing and are accompanied by an irregular ventricular response. "The FABP4 levels also correlate to the extent of left atrial adipose tissue volume in patients with atrial fibrillation." (PMID 37794302, 2024). "A recent publication reported an association between FABP4 and atrial fibrillation, however in our study sample the incidence of atrial fibrillation was only about 20% and we did not observe different rates of atrial fibrillation in patients with lower or higher FABP4 levels." (PMID 32727561, 2020).
chronic obstructive pulmonary disease (5 papers, 2013 to 2023). A chronic and progressive lung disorder characterized by the loss of elasticity of the bronchial tree and the air sacs, destruction of the air sacs wall, thickening of the bronchial wall, and mucous accumulation in the bronchial tree. "This suggests that FABP4 may play an important role in cardiac depolarization and possibly cardiac arrhythmias." (PMID 24455402, 2013). "The present study aimed to examine serum FABP-4 and interleukin (IL)-6 levels in patients with stable and acute exacerbation of chronic obstructive pulmonary disease (COPD) and the correlation of these markers with airflow limitation." (PMID 31905499, 2020). "However, to our knowledge, no data are available in humans on the effects of FABP4 on cardiac arrhythmia." (PMID 24455402, 2013). "Another aim of this study was to evaluate the relationship between serum FABP-4 levels and the severity of disease based on Global Initiative for Chronic Obstructive Pulmonary Disease (GOLD) grades and clinical assessment of disease severity based on COPD Assessment Test (CAT) in patients with COPD." (PMID 31905499, 2020).
colon adenocarcinoma (5 papers, 2021 to 2023). "In research focusing on colon adenocarcinoma, a higher FABP-4 expression has been observed in tumor than in adjacent tissues and FABP4 was part of an 11-gene risk score that predicts recurrence of colon adenocarcinoma." (PMID 37833736, 2023). "However, the relationship between FABP4 expression and tumor immunity in colon adenocarcinoma (COAD) is still poorly understood." (PMID 36264920, 2022). "We also present in boxplot visualizations comparisons of the expressions of FABP genes in normal, colon adenocarcinoma (COAD), and rectal adenocarcinoma (READ) tissues, which showed that the FABP1, FABP4, and FABP6 genes had significantly different expression levels in normal and CRC tissues." (PMID 34680577, 2021).
endometrial cancer (5 papers, 2022 to 2025). Primary or metastatic malignant neoplasm involving the endometrium (mucous membrane that lines the endometrial cavity). "The analysis of mRNA and protein expression in the experiment confirmed that the expression of FABP4 in endometrial cancer tissue was lower than that in normal endometrial tissue." (PMID 36532833, 2022). "Notably, FABP4 exhibits low expression levels in endometrial cancer." (PMID 40107973, 2025). "However, a recent study showed that FABP4 might play a possible suppressive role in endometrial cancer cell proliferation, migration, and invasion through the PI3K/AKT pathway." (PMID 36578551, 2022).
gastric adenocarcinoma (5 papers, 2020 to 2024). "PDL1 blockade in both in vivo and in vitro gastric adenocarcinoma models also increased fatty acid binding protein 4/5 (Fabp4/5) expression in resident memory T cells, improving their survival." (PMID 37180129, 2023). "Then, using the TIMER2.0 database, we investigated the correlation between FABP4 expression and immune infiltration in cancers, especially stomach adenocarcinomas (STAD) and colorectal adenocarcinoma (COADREAD)." (PMID 36532833, 2022). "When the expression of FABP4 and FABP5 in gastric adenocarcinoma tumor cells was down-regulated, the expression of Fabp4/5 in Trm cells was inhibited, and the uptake of lipids by Trm cells increased, thus increasing the survival rate of Trm cells in vitro and vivo." (PMID 35785165, 2022).
glioma (5 papers, 2014 to 2024). A benign or malignant brain and spinal cord tumor that arises from glial cells (astrocytes, oligodendrocytes, ependymal cells). "On the other hand, Hoxa5 and Fabp4, both associated with increased malignancy in gliomas, were upregulated in MYC/SMARCA4 tumors." (PMID 37919824, 2023). "GFAP, NEFL, FABP4 and MMP3 are useful for differential diagnosis and prognosis, and are associated with molecular changes in gliomas." (PMID 38879494, 2024). "In general, the highest levels of the biomarkers are seen in GBM, except FABP4 which is higher in meningiomas vs. gliomas." (PMID 38879494, 2024). "The combination of two markers (GFAP and FABP4) further enhances the discrimination between gliomas and meningiomas." (PMID 38879494, 2024). "FABP4 is expressed in a significantly higher percentage of GBMs in comparison to both normal brain tissues and lower-grade glial tumors." (PMID 36959545, 2023). "Specifically, the nature of the interaction between GFAP and FABP4 and its role in glioma diagnosis and prognosis requires further study." (PMID 36959545, 2023). "We identified 8 plasma proteins which were increased in gliomas vs. meningiomas (GFAP, NEFL, EDDM3B, PROK1, MMP3, CTRL, GP2, SPINT3) and 4 proteins which were decreased in gliomas vs. meningiomas (FABP4, ALDH3A1, IL-12B and OXT)." (PMID 36959545, 2023). "Although we found that the two glioma cell lines had different inhibitory effects on FABP4 at different time points, significant inhibitory effects could be seen at 3, 6, and 12 h." (PMID 35454942, 2022). "As such, an imaging probe targeting FABP4 could also be useful for elucidating how FABP4 functions in glioma and related diseases." (PMID 24732569, 2014). "FABP4 imaging could be useful for diagnosing glioma malignancy and instability of atherosclerotic plaques, to elucidate the detailed function of FABP4 in FABP4-related diseases, and also to develop pharmaceuticals that target FABP4 in these disorders." (PMID 24732569, 2014). "Although FABP4 expressed in cells surrounding the tumor such as adipocytes and macrophages plays an important role in the metabolic microenvironment of glioma and other tumors, we should stress here that the detailed function of FABP4 still remains unclear." (PMID 24732569, 2014). "Therefore, FABP4 is a potential molecular imaging target for evaluating glioma malignancy, for which there are currently few nuclear imaging tools beyond a tritium labeled probe." (PMID 24732569, 2014). "Compared to normal brain tissue and lower-grade glial tumors, in human glioblastoma lesions (GBM, grade 4 glioma) FABP4 was reportedly expressed at significantly higher levels in phagocytic macrophage-like cells (or presumably premature microglias) and microvascular endothelial cells." (PMID 24732569, 2014). "Recently a relationship between FABP4 expression and glioma malignancy was reported." (PMID 24732569, 2014). "This FABP4-targeting probe, which is suitable for single photon emission computed tomography (SPECT), may have valuable applications for evaluating glioma malignancies, elucidating the function of FABP4 and the development of therapeutic agents that target FABP4." (PMID 24732569, 2014). "Interestingly, this model also aggregates the glioma cases by sub-type, with glioblastomas having high GFAP, meningiomas having low GFAP and high FABP4, while anaplastic astrocytomas and oligodendrogliomas display both low FABP4 and low GFAP." (PMID 36959545, 2023).
Hypoglycemia (5 papers, 2013 to 2023). A decreased concentration of glucose in the blood. "The expression and secretion of FABP4 in macrophages are associated with their immune activation, which is less likely to occur during acute hypoglycemia." (PMID 34676825, 2021). "Animal studies using FABP4 knockout mice demonstrated that FABP4 deficiency disrupted the expression of multiple glucagon-regulated pathways, leading to impaired glycogen degradation in hypoglycemia." (PMID 37628833, 2023). "The suppression of adequate rise in FABP4 among LGA neonates may further exacerbate the risk for hypoglycemia associated with LGA." (PMID 34676825, 2021). "As glucose is likely to be an important energy substrate for DKO mice even in the fasted state, our findings imply that marked hypoglycaemia due to fasting and FABP4/5 deficiency (groups 7 and 8) could cause detrimental effects on the exercise performance in fasted DKO mice." (PMID 30866899, 2019). "The immediate correction of hypoglycemia by injection of recFABP4 further supports a necessary hormonal role for FABP4 in maintaining normoglycemia by correcting the impaired glucagon-mediated glycogenolysis as we previously suggested." (PMID 34676825, 2021). "The results showed that, despite a marked hypoglycemia in Fabp4–/– mice, liver glycogen content was comparable to that of normoglycemic Fabp4WT controls." (PMID 34676825, 2021). "Of note, the expression of neither of these genes was reduced, with even a significant increase in G6pc mRNA levels observed in livers of Fabp4–/– mice, which may represent a compensatory adaptation to hypoglycemia in Fabp4–/– mice." (PMID 34676825, 2021). "Thus, the inappropriately intact liver glycogen stores in the setting of substantial hypoglycemia argues in favors of impaired glucagon-induced glycogenolysis in Fabp4–/– mice." (PMID 34676825, 2021). "Indeed, Fabp4–/– liver glycogen was inappropriately intact, despite a marked hypoglycemia, with rapid restoration of normoglycemia upon injection of recombinant FABP4." (PMID 34676825, 2021). "Indeed, despite a marked hypoglycemia observed in Fabp4–/– neonates, liver glycogen stores remained largely intact." (PMID 34676825, 2021). "The robust increase in circulating FABP4 during hypoglycemia and its ability to restore normoglycemia may indicate a role for FABP4 as an additional insulin counterregulatory hormone." (PMID 34676825, 2021). "In addition, neonatal FABP4 levels inversely correlated with blood glucose, with the highest levels recorded in neonates experiencing hypoglycemia." (PMID 34676825, 2021). "This rise in FABP4, which correlates with the drop in blood glucose observed within the first day of life, may indicate an additional hormonal signal in the complex insulin counterregulatory endocrine network, aiming at preventing postnatal hypoglycemia." (PMID 34676825, 2021). "Indeed, the highest levels of FABP4 were recorded in neonate who developed hypoglycemia." (PMID 34676825, 2021). "FA-metabolism-deficient mice, such as KO mice for the MCAD, LCAD, and DECR genes, exhibit metabolic characteristics very similar to those found in the FABP4/5 DKO mice during prolonged fasting (e.g., hypoglycemia, elevated levels of serum NEFAs, and fatty liver)." (PMID 24603714, 2014).
injury (5 papers, 2013 to 2025). Damage inflicted on the body as the direct or indirect result of an external force, with or without disruption of structural continuity. "Although adipose tissue and inflammatory cells such as macrophage are the main secretor sources of FABP-4, it has also been shown that levels of FABP-4 are high in acute lung injury." (PMID 31905499, 2020).
lipodystrophy (5 papers, 2016 to 2023). A congenital or acquired disorder characterized by abnormal loss or redistribution of the adipose tissue in the body. "As Fabp4-Cre is expressed in mature adipocytes as well as preadipocytes (adipo-progenitors), the lipodystrophy of WAT in the Fabp4-Lkb1 KO mice may be due to the key role of Lkb1 in white preadipocyte survival and differentiation." (PMID 27461402, 2016).
liver inflammation (5 papers, 2021 to 2023). "The up-regulated level of FABP4 in the systemic circulation of patients with NAFLD is associated with liver inflammation and fibrosis." (PMID 37950277, 2023). "Furthermore, overexpressing FABP4 in hepatic tumor cell lines inhibited tumor expansion in an ectopic mouse model in vivo." (PMID 36358315, 2022). "Moreover, one study discovered correlations of IR and liver inflammation and fibrosis severity with elevated FABP4 levels in patients with NAFLD." (PMID 34206460, 2021). "Besides, the level of FABP4 in the systemic circulation is up-regulated in patients with NAFLD, which is associated with liver inflammation and fibrosis." (PMID 34803493, 2021).
metastatic tumors (5 papers, 2019 to 2025). "There was a significant difference in the expression of FABP4 between primary and metastatic tumors." (PMID 37978381, 2023). "The results showed that CAFs in metastatic tumors expressed high levels of KRT15, FABP4, S100A8, and COL18A1 and were associated with high enrichment of vasculature development, cell population proliferation, and epithelial cell differentiation." (PMID 36569924, 2022). "The molecular mechanism that distinguished metastatic tumors from primary tumors relied predominantly on the fatty acid binding protein 4 (FABP4)." (PMID 31769430, 2019). "Typically, FABP4 expression was higher in metastatic tumors but lower in primary tumors." (PMID 37978381, 2023).
neuroblastoma (5 papers, 2021 to 2025). Neuroblastoma (NB) is the most common solid, extracranial childhood tumor. "The expression of FABP4 in macrophages is associated with poor prognosis, and it may inactivate the NF-κB-IL1α pathway, thereby promoting the proliferation and migration of neuroblastoma cells." (PMID 36532833, 2022). "Another study has found that high levels of FABP4 predict a poor prognosis for neuroblastoma." (PMID 36060264, 2022). "Fatty Acid Binding Protein 4 (FABP4) in TAMs may contribute to hepatic metastasis formation by inactivating the NF-κB-IL1α pathway through ubiquitination of ATPB, thereby promoting the proliferation and migration of neuroblastoma cells (NB)." (PMID 40034694, 2025).
peripheral arterial disease (5 papers, 2020 to 2025). A disorder of the arteries supplying the upper and lower extremity and the visceral organs. "Noteworthily, increased circulating FABP4 concentrations were found significantly associated with all-cause death in subjects with T2D, and all-cause mortality was associated with the highest tertile of FABP4 concentrations in subjects with peripheral arterial disease." (PMID 36978893, 2023).
thyroid cancer (5 papers, 2022 to 2025). "We found that DPP4, TIMP1 and TYRO3 were associated with a better prognosis and survival in patients with thyroid cancer, while FABP4, NR4A1 and SNCA were associated with a poor prognosis and survival in patients with thyroid cancer." (PMID 36407322, 2022). "First, FN1, IDH2, and VDAC1 were more highly expressed in thyroid cancer tissues than in normal tissues; however, FABP4 and TG were less highly expressed in thyroid cancer tissues." (PMID 36418670, 2023). "FABP4 has good predictive value for the prognosis of thyroid cancer patients and may serve as a clinical biomarker for diagnosis and prognosis." (PMID 40717587, 2025). "Thyroid cancer: FABP4 mRNA and protein levels are reduced in PTC and FTC and may serve as potential indicators of thyroid cancer development." (PMID 40717587, 2025).
Arrhythmia (4 papers, 2013 to 2024). Any cardiac rhythm other than the normal sinus rhythm. "Multivariate logistic regression analysis was then used to evaluate the effects of plasma FABP4 level and other risk factors for arrhythmia in the patients with an abnormal QTc interval." (PMID 31234795, 2019).
bronchopulmonary dysplasia (4 papers, 2011 to 2022). Bronchopulmonary dysplasia is a chronic respiratory disease that results from complications related to lung injury during the treatment of infant acute respiratory distress syndrome in low-birth-weight premature infants or from abnormal lung development in older infants. "For example, FABP4 is highly expressed in hyperoxic lung injury and may be implicated in bronchopulmonary dysplasia." (PMID 35706027, 2022). "In addition, increased levels of FABP4 have also been found in inflammation-induced bronchopulmonary dysplasia and hyperoxia-induced lung injury." (PMID 35706027, 2022). "Recently, FABP4 has been reported to be detected in lungs and bronchoalveolar samples from patients with bronchopulmonary dysplasia (BPD)." (PMID 22121495, 2011).
Cerebral ischemia (4 papers, 2021 to 2025). Restriction of arterial blood supply to the brain associated with insufficient oxygenation to support the metabolic requirements of the tissue. "Recently, FABP4 mAb 6H2 effectively blocked FABP4-induced cerebral ischemia injury." (PMID 41392988, 2025). "In a cerebral ischemia injury model, FABP4 promotes MMP-9 expression through JNK/c-Jun signaling." (PMID 34685761, 2021).
glioblastoma (4 papers, 2013 to 2023). The most malignant astrocytic tumor (WHO grade IV). "Next, we evaluated the in vivo capacity of [125I]TAP1 to recognize FABP4 in normal and glioblastoma-bearing mice." (PMID 24732569, 2014). "Overexpression of FABP4 has also been reported in glioblastoma." (PMID 30526555, 2018). "FABP4 expression was recently reported for glioblastoma, where it may participate in disease malignancy." (PMID 24732569, 2014).
osteoporosis (4 papers, 2020 to 2026). A condition of reduced bone mass, with decreased cortical thickness and a decrease in the number and size of the trabeculae of cancellous bone (but normal chemical composition), resulting in increased fracture incidence. "Several new genes, including FABP4, were found in common between deer cyclic and human pathological osteoporosis." (PMID 34356534, 2021). "In our study, JGSQP activated the expression of p-AKT along with multiple bone formation and adipogenesis-related genes (Wnt10b, Osx, BMP2, PPARγ, Fabp4, and Fndc5), suggesting that it may ameliorate murine OVX-induced osteoporosis with KYD by controlling the bone-fat balance via the AKT pathway." (PMID 32963560, 2020).